RN7SL782P (RNA, 7SL, cytoplasmic 782, pseudogene)
Gene: Miscellaneous RNA gene on chromosome 5 (107,734,773 to 107,735,066, reverse strand). Ensembl gene ENSG00000239708.
Homologues: Orthologues: chimpanzee Metazoa_SRP (99% identical), macaque Metazoa_SRP (91% identical). Paralogues in human: RN7SL2 (82% identical), RN7SL1 (81% identical), RN7SL3 (80% identical), RN7SL566P (79% identical), RN7SL47P (78% identical), RN7SL498P (78% identical), RN7SL743P (78% identical), RN7SL14P (78% identical), RN7SL797P (78% identical), RN7SL218P (77% identical), RN7SL408P (77% identical), RN7SL444P (77% identical), and 702 more.